SCGB3A2 (secretoglobin family 3A member 2)
Description:
Secreted cytokine-like protein. Binds to the scavenger receptor MARCO. Can also bind to pathogens including the Gram-positive bacterium L.monocytogenes, the Gram-negative bacterium P.aeruginosa, and yeast. Strongly inhibits phospholipase A2 (PLA2G1B) activity. Seems to have anti-inflammatory effects in respiratory epithelium (By similarity). Also has anti-fibrotic activity in lung. May play a role in fetal lung development and maturation. Promotes branching morphogenesis during early stages of lung development. In the pituitary, may inhibit production of follicle-stimulating hormone (FSH) and luteinizing hormone (LH) (By similarity).
Synonyms: PnSP-1; PNSP1; UGRP1; LU103
Tractability: Antibody: UniProt places it where antibodies can reach, with high confidence; its Gene Ontology location is reachable by antibodies, with high confidence; UniProt predicts a signal peptide or a membrane-spanning region.
Gene: Protein-coding gene on chromosome 5 (147,869,800 to 147,882,197, forward strand). Ensembl gene ENSG00000164265.
Subcellular location: Secreted
Pathways (Reactome):
Vesicle-mediated transport: Scavenging by Class A Receptors
Gene Ontology:
Cellular component: extracellular region; endocytic vesicle lumen
Genetic constraint (gnomAD): Loss-of-function variants: 3 observed, 6.27 expected, observed/expected ratio (o/e) 0.48, 90% interval 0.22 to 1.23. That is too few expected variants to judge how well the gene tolerates losing a copy. Missense variants: 95 observed, 88.42 expected, observed/expected ratio (o/e) 1.07, 90% interval 0.91 to 1.27. Synonymous variants: 36 observed, 36.86 expected, observed/expected ratio (o/e) 0.98, 90% interval 0.75 to 1.29.
Homologues: Orthologues: chimpanzee SCGB3A2 (100% identical), macaque SCGB3A2 (89% identical), pig SCGB3A2 (86% identical), rat Scgb3a2 (80% identical), rabbit SCGB3A2 (76% identical), dog SCGB3A2 (74% identical), mouse Scgb3a2 (73% identical). Paralogues in human: SCGB3A1 (47% identical).
Diseases named in the same sentence as SCGB3A2 in open-access papers:
SCGB3A2 is named in the same sentence as 46 diseases in open-access papers, as found by Europe PMC text mining. Sharing a sentence is not in itself a finding about the gene and the disease. The quoted sentences say what the papers report.
asthma (7 papers, 2011 to 2023). "Genetic analysis has demonstrated that a single nucleotide polymorphism (SNP) (G/A) at -112bp of the human SCGB3A2 (UGRP1) gene promoter is associated with an increased risk of asthma in a Japanese population." (PMID 21385388, 2011). "SCGB3A2 is a small secretory protein that is predominantly expressed in airway epithelial Club cells, It has anti-inflammatory, growth factor, anti-fibrotic and anti-cancer activities that influence various lung diseases including asthma." (PMID 37329449, 2023). "In this study, several genes including Gdpd2, Spon2, Pon1, Scgb3a2, Ighv2-3, Sult1d1, Cyp2f2, Npas2, Arntl, and Igkv4-68 were down-regulated in OVA-challenged mice compared with control mice, may be useful as biomarkers of asthma." (PMID 29086354, 2018).
pulmonary fibrosis (6 papers, 2015 to 2023). Chronic progressive interstitial lung disorder characterized by the replacement of the lung tissue by connective tissue, leading to progressive dyspnea, respiratory failure, or right heart failure. "Scgb3a2-null mice are more susceptible to BLM-induced pulmonary fibrosis as compared to wild-type mice." (PMID 26559674, 2015). "Scgb3a2-null mice are more susceptible to BLM-induced pulmonary fibrosis, thus establishing that SCGB3A2 exhibits anti-fibrotic activity." (PMID 26559674, 2015). "In contrast, another study by Kadur Lakshminarasimha Murthy and colleagues found that AEC2s can convert to SCGB3A2+ cells in organoid cultures and de novo in human lungs after injury and in diseases including idiopathic pulmonary fibrosis and COPD." (PMID 37966116, 2023). "In contrast, over-expression of SCGB3A2, a club cell marker with heterogeneous expression, in mouse lung accelerates resolution of bleomycin-induced pulmonary fibrosis." (PMID 32941426, 2020). "The proportion of SCGB3A2+ only cells was increased and widespread in the cystic and fibrotic lesions of pulmonary fibrosis tissue sections." (PMID 32941426, 2020). "Exogenous Scgb3a2 administration has been shown to suppress bleomycin-induced pulmonary fibrosis via TGF-β signaling downregulation." (PMID 28936122, 2017). "This study was initiated to revisit the anti-fibrotic role of SCGB3A2 using Scgb3a2-null mice in the BLM-induced pulmonary fibrosis model." (PMID 26559674, 2015). "These are very similar phenotypes to what was found for the Scgb3a2-null mice in the BLM-induced pulmonary fibrosis model." (PMID 26559674, 2015). "Histological examination revealed that both BLM-treated wild-type and Scgb3a2-transgenic mice developed extensive pulmonary fibrosis by 3 weeks based on a whole lung H&E stained images and Masson Trichrome staining." (PMID 26178733, 2015). "In a previous study, exogenously administered human recombinant SCGB3A2 showed a similar effect in suppressing BLM-induced pulmonary fibrosis using mouse model, suggesting that human SCGB3A2 most likely suppresses pulmonary fibrosis in humans." (PMID 26559674, 2015). "Anti-fibrotic activity of SCGB3A2 was demonstrated using bleomycin (BLM)-induced pulmonary fibrosis mouse model, in conjunction with intravenous administration of SCGB3A2." (PMID 26559674, 2015). "Scgb3a2-transgenic and wild-type mice were subjected to bleomycin-induced pulmonary fibrosis model, and their lungs and bronchoalveolar lavage fluids were collected at various time points during 9 weeks post-bleomycin treatment for further analysis." (PMID 26178733, 2015). "On the other hand, anti-fibrotic activity of SCGB3A2 was demonstrated by using a bleomycin (BLM)-induced mouse pulmonary fibrosis model." (PMID 26178733, 2015). "In this study, the role of SCGB3A2 was examined using Scgb3a2-null mice in the BLM-induced pulmonary fibrosis model." (PMID 26559674, 2015). "The pulmonary fibrosis in the Scgb3a2-null mice was more severe than the wild-type controls, thus establishing that SCGB3A2 has anti-fibrotic activity in vivo." (PMID 26559674, 2015). "Previously, the anti-fibrotic activity of SCGB3A2 was demonstrated by exogenously administering SCGB3A2 to BLM-induced pulmonary fibrosis model mice." (PMID 26559674, 2015). "Interestingly, this study also proposed an approach in which AEC2-derived SCGB3A2+ cells contribute to ectopic bronchiolar structures found in idiopathic pulmonary fibrosis." (PMID 37966116, 2023). "How SCGB3A2 promotes natural resolution of BLM-induced pulmonary fibrosis requires further studies." (PMID 26178733, 2015). "Since SP-C is a marker for alveolar type II cells, the promoter for this gene was used for transgenic over-expression of SCGB3A2 in the alveolar areas because in a previous study using the BLM-induced pulmonary fibrosis model, pulmonary fibrosis was reduced by intravenous administration of SCGB3A2." (PMID 26178733, 2015).
pulmonary fibrosis (continued). "Importantly, surfactant proteins and SCGB1A1 appear not to be involved in the susceptibility of Scgb3a2-null mice to BLM-induced pulmonary fibrosis." (PMID 26559674, 2015). "Thus, SCGB3A2 has an anti-fibrotic activity, and potentially may be of value in the treatment of pulmonary fibrosis in humans." (PMID 26559674, 2015). "Both mouse and human recombinant SCGB3A2 proteins exhibited similar levels of anti-fibrotic activity when intravenously administered to mice in the BLM-induced pulmonary fibrosis model, suggesting that SCGB3A2 may be clinically relevant to treat pulmonary fibrosis in humans." (PMID 26559674, 2015). "Mice null for the Scgb3a2 gene were subjected to the BLM-induced pulmonary fibrosis model, and the severity of pulmonary fibrosis determined using histological and biochemical methods." (PMID 26559674, 2015). "The role of SCGB3A2 in fibrosis was revisited using Scgb3a2-null mice and littermate controls in the BLM-induced pulmonary fibrosis model." (PMID 26559674, 2015). "When these mice were subjected to the BLM-induced pulmonary fibrosis model, a slightly exaggerated fibrosis was initially noted at 3 weeks post-BLM, however the fibrosis more rapidly resolved in Scgb3a2-transgenic mice as compared to wild-type by 6 weeks post-BLM." (PMID 26178733, 2015). "In order to examine whether Scgb3a2-transgenic mice exhibit any phenotypes upon challenge, both wild-type and Scgb3a2-transgenic mice were subjected to the BLM-induced pulmonary fibrosis model." (PMID 26178733, 2015). "There results suggest that the lack of SCGB3A2 expression, but not those of surfactant proteins and SCGB1A1 is likely to result in increased susceptibility of Sgb3a2-null mice to BLM-induced pulmonary fibrosis." (PMID 26559674, 2015).
lung carcinoma (5 papers, 2016 to 2023). "RNA sequencing revealed a number of genes differentially expressed in lung tumors lacking Akt2 and five of these genes, Actc1, Bpifa1, Mmp2, Ntrk2, and Scgb3a2 have been implicated in human lung cancer." (PMID 26654940, 2016). "For comparison, human lung cancer specimens were also subjected to the IHC assays for the detection of SCGB3A2." (PMID 37509714, 2023). "The expression of SCGB3A2 was reported in human lung carcinomas, suggesting its use as a tumor marker." (PMID 37509714, 2023). "The Cancer Genome Atlas (TCGA) database was used to analyze the expression of SCGB3A2 among various lung cancers." (PMID 33452234, 2021). "In a study, SCGB3A2 expression was compared with NKX2-1 expression in lung cancer." (PMID 37509714, 2023). "In addition, while fibrosis is closely related to tumor development and SCGB3A2 functions as an anti-fibrotic agent, the role of SCGB3A2 in lung cancer development is unknown." (PMID 30526845, 2018). "SCGB3A2 (also named uteroglobin-related protein 1, UGRP1 and high in normal-2, HIN-2), the first member of the SCGB gene superfamily, that is highly expressed in airway epithelial Club cells with various biological functions, including anti-lung cancer activity." (PMID 36523974, 2022). "In order to investigate whether SCGB3A2 inhibits metastatic growth of human cancer cells, a lung cancer intravenous metastasis model using NSG (non-obese diabetic (NOD) scid gamma) mice was employed." (PMID 33452234, 2021).
Graves disease (2 papers, 2014 to 2019). Graves' disease is an autoimmune disorder that leads to overactivity of the thyroid gland (hyperthyroidism).It is caused by an abnormal immune system response that causes the thyroid gland to produce too much thyroid hormones. "PTPN22, IL-2RA/CD25, CD40, and SCGB3A2 genes were shown to be associated with Graves’ disease (GD) using candidate gene studies." (PMID 31066758, 2019).
lung adenocarcinoma (2 papers, 2021). A carcinoma that arises from the lung and is characterized by the presence of malignant glandular epithelial cells. "TCGA analysis results support the notion that SCGB3A2 suppresses the growth of cancer cells in humans, particularly lung adenocarcinomas." (PMID 33452234, 2021). "TCGA analysis revealed that lung adenocarcinoma patients with higher SCGB3A2 mRNA levels exhibited better survival." (PMID 33452234, 2021). "The survival rate of lung adenocarcinoma patients expressing high levels of SCGB3A2 was higher than those with low expression." (PMID 33452234, 2021). "Further, among all lung adenocarcinoma patients analyzed, three patients expressed high levels (upper 20%) of all three critical genes SCGB3A2, SDC1, and CASP4, and all of them survived up to 40 months, although the “n” number is too small to establish significance." (PMID 33452234, 2021). "The results suggest that SCGB3A2 may be a good prognostic marker for lung adenocarcinomas." (PMID 33452234, 2021).
lung diseases (2 papers, 2022 to 2023). "Other studies have found that secretoglobin family 3A member 2 is a small, secreted protein of about 10 kDa that forms dimers and tetramers, has anti-inflammatory, growth factor, anti-fibrotic, and anticancer activities, and can affect various lung diseases." (PMID 36079904, 2022).
melanoma (2 papers, 2018 to 2021). A malignant, usually aggressive tumor composed of atypical, neoplastic melanocytes. "Previously, we showed that LLC cells have high expression of SDC1 and CASP11, with strong susceptibility to SCGB3A2-induced anti-tumor activity, whereas B16F10 melanoma cells have very little expression of SDC1 and CASP11, and no susceptibility to SCGB3A217." (PMID 33452234, 2021).
non-small cell lung carcinoma (2 papers, 2019 to 2021). A group of at least three distinct histological types of lung cancer, including non-small cell squamous cell carcinoma, adenocarcinoma, and large cell carcinoma. "We found that SCGB3A2 exhibits a potent anti-tumorigenic effect in some cancer types, especially non-small-cell lung cancers (NSCLCs) and epithelial-derived colorectal cancers." (PMID 33452234, 2021). "SCGB3A2 has been identified as a marker for pulmonary carcinoma in mice and humans, and MARCO has recently been identified as a possible candidate for targeted antibody therapy in non-small cell lung cancer." (PMID 31014259, 2019).
atherosclerosis (1 paper, 2020). A disease characterized by the build-up of fatty material and calcium deposition in the arterial wall resulting in partial or complete occlusion of the arterial lumen. "Patients with STEMI had higher secretoglobin family 3A member 2 and tartrate-resistant acid phosphate type 5 and lower platelet-derived growth factor subunit A, which are proteins associated with atherosclerosis severity and plaque development mediated via altered phospholipid metabolism." (PMID 33396480, 2020).
chronic rhinosinusitis (1 paper, 2011). Chronic form of sinusitis. "The aim of this study was to investigate the expression regulation of SCGBs other than SCGB1A1 (CC10) in human upper airway, and their potential involvement, particularly that of SCGB3A2 (UGRP1), in chronic rhinosinusitis (CRS) with nasal polyps (CRSwNP) and without nasal polyps (CRSsNP)." (PMID 21385388, 2011).
colon cancers (1 paper, 2021). "Two epithelial-derived colon cancer cell lines expressing SDC1 and CASP4 were also susceptible to SCGB3A2-LPS treatment." (PMID 33452234, 2021).
colorectal cancer (1 paper, 2021). A primary or metastatic malignant neoplasm that affects the colon or rectum. "It is notable that both NSCLC and epithelial-derived colorectal cancer cells showed strong responses to SCGB3A2." (PMID 33452234, 2021). "Two human epithelial-derived colorectal cancer cells (HCT116 and SW620) also showed susceptibility to SCGB3A2 + LPS by CCK8 assay in vitro." (PMID 33452234, 2021). "Of the 13 human cancer cell lines examined, 5 NSCLCs (NCI-H596, H358, H322, A549, and H157) and 2 colorectal cancers (HCT116 and SW620) showed approximately 20% growth reduction by SCGB3A2 + LPS." (PMID 33452234, 2021).
fibrosis (1 paper, 2015). the formation of excess fibrous connective tissue in an organ or tissue in a reparative or reactive process. "Hematoxylin & Eosin, Masson Trichrome, and Sirius Red staining of lung sections, Ashcroft fibrosis scores, hydroxyproline contents, and the levels of mRNAs encoding various collagens demonstrated that BLM-treated Scgb3a2-null mouse lungs had more severe fibrosis than those of wild-type mouse lungs." (PMID 26559674, 2015).
lung adenoma (1 paper, 2025). A benign, well circumscribed epithelial neoplasm that arises from the bronchus or the lung parenchyma. "The differentially expressed genes in CPAM samples are mainly related to genes associated with airway epithelial cells, such as SCGB1A1, SCGB3A2, AGR3, and increased expression levels of these genes may be associated with proliferation and differentiation of lung adenoma cells." (PMID 40529122, 2025).
myeloma (1 paper, 2018). "After stimulation with SCGB3A2, the SDC1 signal became relatively concentrated on cell protrusions equivalent to the uropod structure of myeloma, which co-localized with SCGB3A2 (+SCGB3A2)." (PMID 30526845, 2018).
Obesity (1 paper, 2022). Accumulation of substantial excess body fat. "In lab studies, we found that obesity reduced the numbers of CC16- and SCGB3A2-expressing cells in the airways." (PMID 35768822, 2022). "Additionally, we examined the number of SCGB3A2 (another biomarker of club cells)-expressing cells and found reduced numbers in the airways of humans and mice with obesity compared to those in controls without obesity." (PMID 35768822, 2022).
tumor (10 papers, 2016 to 2025). "This indicates that the SDC1/CASP11 expression patterns could determine the susceptibility of cancer cells to SCGB3A2-induced anti-tumor activity." (PMID 33452234, 2021). "SCGB3A2 significantly reduced the growth of all three NSCLC cells in the mouse metastasis model as determined by a percentage of tumor area per total area." (PMID 33452234, 2021). "These mice developed more tumors than normal mice, but tumor growth was suppressed when mice were injected with SCGB3A2." (PMID 30526845, 2018). "Furthermore, SCGB3A2 reportedly induces tumor regression in C57BL/6 mice with murine Lewis lung carcinoma (LLC) cells." (PMID 34522213, 2021). "Our qRT‐PCR results revealed that the expression levels of TNFSF10 (p < 0.01), ECM1 (p < 0.01), and RNF213 (p < 0.01) were significantly increased in advanced LUAD tumor cells, whereas the expression of SCGB3A2 (p < 0.01), SCGB3A1 (p < 0.01), and SFTPC (p < 0.01) was increased in early LUAD." (PMID 33783985, 2021). "In addition to the change of tumor volume, tumor metastasis was also affected by the interaction between SCGB3A2 and SDC1." (PMID 31616642, 2019). "SCGB3A2 is a member of the secretoglobin family of proteins, which share a common four helical bundle subunit structure, exist as dimers, tetramers, and other oligomers, and some of which have also been implicated in tumor suppression without a clear understanding yet of the mechanistic pathway(s)." (PMID 30526845, 2018). "Assessment of epithelial marker genes showed similar expression scores across fresh and FFPE tissue samples, as EPCAM, KRT5, SCGB3A2, FOXJ1, AGER and SFTPC marked tumor epithelial, Basal, Transitional, Ciliated, AT1, and AT2 cells, respectively, across the datasets." (PMID 38300468, 2024). "In the tumour activation samples, SCGB3A1 and SCGB3A2, were highly expressed." (PMID 39187937, 2024). "By visualising the ligand-receptor signalling networks underlying this communication, we identified that interactions between tumour cells and both non-classical and intermediate monocytes were primarily mediated by the APP-CD74 and SCGB3A2-MARCO signalling axes." (PMID 41425578, 2025).